HOXC4 (homeobox C4)
Diseases named in the same sentence as HOXC4 in open-access papers (continued):
Sharing a sentence is not in itself a finding about the gene and the disease.
cancer (13 papers, 2017 to 2025). A tumor composed of atypical neoplastic, often pleomorphic cells that invade other tissues. "The survival analysis revealed that HOXC4 upregulation in several cancers was associated with a worse prognosis." (PMID 41465326, 2025). "In summary, we found that HOXC4 expression differs significantly among tissue types, and that overexpression of HOXC4 is significantly associated with poorer clinical outcomes in pan-cancer." (PMID 36276951, 2022). "Although the evaluation of immune cell infiltration has been implicated in various cancers of prognostic significance and cancer-targeted immunotherapy potential, the critical role of HOXC4 expression in TME warrants further investigation." (PMID 36276951, 2022). "On the other hand, Kaplan–Meier curves comparing OS in these six cancers suggested an association between increased HOXC4 expression and a worse prognosis." (PMID 36276951, 2022). "Methylated regions in a gene collection that includes HOXC4 were considered important in estimating cancer risk in urothelium and as part of a prognostic signature predicting survival in patients with oral squamous cell carcinoma." (PMID 32635388, 2020). "The outcome of survival analysis including overall survival (OS), disease-free interval (DFI), disease-specific survival (DSS) and progression-free interval (PFI) revealed that upregulation of HOXC4 expression in several cancers was associated with worse prognosis." (PMID 36276951, 2022). "The findings of this study suggest that HOXC4 may serve as a latent candidate for therapeutic target associated with immunological strategies in a wide variety of cancer types, apart from serving as a prognostic biomarker." (PMID 36276951, 2022). "Careful interpretation is necessary, as HOXC4 has been identified as an oncogene in various cancers." (PMID 39766812, 2024). "We will conduct further basic experimental verification in our subsequent research and HOXC4’s biological activity in different cancer cells will then be explored, such as proliferation and/or migration." (PMID 36276951, 2022). "According to our previous description, HOXC4 plays a vital role during embryonic development and in the development of cancer." (PMID 36276951, 2022). "Collectively, HOXC4 plays an important oncogenic role in the development and progression of cancers, as well as in the regulation of these signaling pathways." (PMID 36276951, 2022). "As a result of our comprehensive pan-cancer study, we have identified a significant link between the expression of HOXC4 and the efficacy of immunotherapy-related treatments, together with anti-cancer drug sensitivity." (PMID 36276951, 2022). "Since TCGA samples of normal tissues were limited, GTEx and TCGA data were then integrated to estimate the HOXC4 expression difference across different cancer types." (PMID 36276951, 2022). "It has been shown that HOXC4 expression is significantly correlated with DFI for patients with four types of cancer, including ACC (p = 0.021, HR = 1.2), LGG (p = 0.029, HR = 1.13), PRAD (p = 0.0048, HR = 1.04) and STAD (p = 0.037, HR = 1.03)." (PMID 36276951, 2022). "We analyzed the relationship between MSI and HOXC4 expression across multiple cancer types using MSI data downloaded from TCGA database." (PMID 36276951, 2022). "Overall, a combined analysis of pan-cancer results reveals that HOXC4 is aberrantly expressed across a variety of cancer types." (PMID 36276951, 2022). "In conclusion, HOXC4 expression is intimately correlated with tumorigenesis and genes involved in immunity in pan-cancer, supporting the importance of HOXC4 in immune modulation and immunotherapy." (PMID 36276951, 2022). "Most genes from the HOXC cluster have been identified as hypermethylated in cancer (HOXC4, C5, C6, C8, C9)." (PMID 32635388, 2020).
cancer (continued). "Abnormal overexpression of HOXC4 in different types of cancer (pancancer study), including SqCLC, suggests that HOXC4 may function as an oncogene and could be used as a diagnostic and prognostic biomarker." (PMID 38398111, 2024). "Hence, infiltrating immune cells can be regulated by HOXC4 expression during different types of cancer development and immune escape can be influenced." (PMID 36276951, 2022). "Moreover, apoptosis and cell cycle were found to be positively involved in OV, and negatively correlated with DNA repair, hypoxia, proliferation, and stemness, greatly broadening our vision of HOXC4 functional states in cancers." (PMID 36276951, 2022). "As a result, HOXC4 may be able to regulate genes involved in the repair-related genes regarding DNA replication errors to improve survival capability of cancer cells." (PMID 36276951, 2022). "Thus, abnormally high levels of HOXC4 expression appear to be crucial for multiple cancers to form and develop." (PMID 36276951, 2022). "Collectively, the expression level of HOXC4 may be involved significantly in immune regulation and immunological events across pan-cancer." (PMID 36276951, 2022). "Further, differential chemosensitivity responses of different cancers could be reflected by upregulation of HOXC4 expression, which could facilitate better tailoring of anticancer therapies." (PMID 36276951, 2022). "Abnormal expression of HOXC4 has been reported in several types of cancers." (PMID 35254502, 2022). "It was found that HOXC4 expression correlated with patient OS in six cancer types, including ACC (p = 3.4e-03, HR = 1.16), COAD (p = 4.2e-02, HR = 1.06), LGG (p = 1.1e-14, HR = 1.09), PAAD (p = 8.6e-03, HR = 1.08), READ (p = 2.3e-02, HR = 1.1), and UVM (p = 1.8e-02, HR = 1.29)." (PMID 36276951, 2022). "As yet, little is known about the critical role of HOXC4 in pan-cancer." (PMID 36276951, 2022). "Accordingly, the positive correlation of higher HOXC4 expression with IC50 values may indicate that elevated HOXC4 expression may result in anti-cancer drug resistance and lower chemosensitivity." (PMID 36276951, 2022). "Furthermore, HOXC4 can play a crucial role in determining the oncogenic validity of immune cells and immune-related genes in various cancers, particularly through their co-expression analyses." (PMID 36276951, 2022). "In addition to very rare germline variants in genes related to liver function, such as HOXC4, PRSS56, and CYP1A1, the patient carried two variants strongly predicted to be deleterious affecting BRCA1 and FAH, both genes associated with cancer predisposition." (PMID 32432034, 2020). "Also, few studies have detected the association between HOXC4 and MSI in cancers." (PMID 36276951, 2022). "It is also noteworthy that the expression of HOXC4 is strongly related to the expression of TMB, MSI, MMR mutation genes, DNA methyltransferases, immune-related markers, and immune checkpoint markers across a broad spectrum of cancer types, all of which affect immunotherapy-related treatment." (PMID 36276951, 2022). "Hence, by assessing different anti-cancer drug responses in various patients based on their HOXC4 expression levels, we may eventually be able to improve our individual therapeutic treatment." (PMID 36276951, 2022). "Therefore, HOXC4 expression may play an integral role in determining patients’ prognoses across a variety of cancer types." (PMID 36276951, 2022). "Further, significant correlation between HOXC4 and patients’ PFI was observed in four types of cancer, including ACC (p = 1.1e-14, HR = 1.09), LGG (p = 3.1e-18, HR = 1.09), LIHC (p = 1.5e-2, HR = 1.11), and PRAD (p = 5.1e-04, HR = 1.03)." (PMID 36276951, 2022). "The involvement of HOXD10, HOXD11, HOXD1, HOXC4, HOXC10, and HOXA11, in the cell cycle and the EMT, confirm their role in the cancer-related signaling pathways." (PMID 35562533, 2022).
cancer (continued). "In addition, significantly higher expression of HOXC4 was detected in CCA, significantly lower expression of RNF135 in HCC and significantly lower expression of OSMR in CRLM compared to the other cancers." (PMID 39766812, 2024). "Furthermore, our findings suggest that HOXC4 strongly correlates with TME, including an increase in the level of infiltration of six immune cells across a variety of cancers." (PMID 36276951, 2022). "In addition, HOXC4 triggers similar molecular alterations as HOXB4 and also is involved in some cancers." (PMID 28852427, 2017). "However, HOXC4 is not well understood as a molecular biomarker in pan-cancer, nor its expression level." (PMID 36276951, 2022). "As yet, no prognostic value has been determined for HOXC4 expression in cancer patients." (PMID 36276951, 2022). "Analysis of DEHGs in oncogenic pathways using GSCALite26 indicated that HOXD10, HOXD11, HOXD1, HOXC4, HOXC10, and HOXA11 may have a crucial role in the activation of epithelial-mesenchymal transition (EMT) in cancer, represented in the form of heatmap percentage." (PMID 35562533, 2022).
HOXC4 also shares sentences with these, for which no sentence is quoted: colon adenocarcinoma (2 papers); leukemia (2); liver cancer (2); rectum adenocarcinoma (2); retinoblastoma (2); thyroid carcinoma (2); allergic disease (1); anal atresia (1); asthma (1); brain disorder (1); Chiari malformation (1); cholangiocarcinoma (1); congenital heart disease (1); ependymoma (1); Esophageal atresia (1); glioblastoma multiforme (1); melanoma (1); metastatic cancers (1); osteoporosis (1); ovarian carcinoma (1); pancreatic adenocarcinoma (1); pancreatic ductal adenocarcinoma (1); prostate adenocarcinoma (1); scleroderma (1); Stroke (1).